KRT27 (keratin 27)
Description:
Essential for the proper assembly of type I and type II keratin protein complexes and formation of keratin intermediate filaments in the inner root sheath (irs).
Synonyms: KRT25C; K25IRS3
Tractability: PROTAC: ubiquitination databases record sites on it.
Gene: Protein-coding gene on chromosome 17 (40,776,808 to 40,782,550, reverse strand). Ensembl gene ENSG00000171446.
Subcellular location: Cytoplasm
Pathways (Reactome):
Developmental Biology: Formation of the cornified envelope; Keratinization
Gene Ontology:
Molecular function: protein binding; structural constituent of skin epidermis; structural molecule activity
Biological process: epithelial cell differentiation; hair follicle morphogenesis; intermediate filament organization; morphogenesis of an epithelium
Cellular component: extracellular exosome; cytoplasm; cytoskeleton; cytosol; keratin filament
Genetic constraint (gnomAD): Loss-of-function variants: 29 observed, 47.51 expected, observed/expected ratio (o/e) 0.61, 90% interval 0.45 to 0.83. The upper end of that interval is the gene's LOEUF score, 0.83, which puts it in group 3 of 6, group 1 being the genes least tolerant of losing a copy. Missense variants: 583 observed, 557.94 expected, observed/expected ratio (o/e) 1.04, 90% interval 0.98 to 1.12. Synonymous variants: 193 observed, 220.79 expected, observed/expected ratio (o/e) 0.87, 90% interval 0.78 to 0.99.
Homologues: Orthologues: chimpanzee KRT27 (99% identical), macaque KRT27 (98% identical), dog KRT27 (92% identical), pig KRT27 (91% identical), rat Krt27 (88% identical), mouse Krt27 (87% identical), guinea pig KRT27 (75% identical). Paralogues in human: KRT25 (80% identical), KRT28 (77% identical), KRT26 (73% identical), KRT10 (58% identical), KRT24 (55% identical), KRT14 (52% identical), KRT15 (51% identical), KRT16 (50% identical), KRT12 (50% identical), KRT17 (48% identical), KRT13 (48% identical), KRT9 (45% identical), and 56 more.
Diseases named in the same sentence as KRT27 in open-access papers:
KRT27 is named in the same sentence as 8 diseases in open-access papers, as found by Europe PMC text mining. Sharing a sentence is not in itself a finding about the gene and the disease. The quoted sentences say what the papers report.
staphylococcus aureus infection (2 papers, 2020 to 2024). An infectious process in which the bacteria Staphylococcus aureus is present. "Notably, Staphylococcus aureus infection was identified as one of the key pathways in which Cluster35 participated, due to its influence on several Keratin-related genes, such as KRT13, KRT23, and KRT27." (PMID 38448858, 2024).
breast carcinoma (1 paper, 2022). "Few studies have shown the prognostic value of CBWD1, CWC25, IFNA2, KRT27, or ZDHHC21 in breast cancer, and subsequent studies are expected." (PMID 36077687, 2022).
hypotrichosis 8 (1 paper, 2023). Any hypotrichosis in which the cause of the disease is a mutation in the LPAR6 gene. "In addition, some paralog genes Krt25, Krt27, Krt72, Krt75, and Krt85, which also participate in the formation of keratin intermediate filaments in the IRS, could be related to Woolly Hair, Autosomal Recessive 3, and Hypotrichosis 8, which were significantly decreased in Krt71–KO mice." (PMID 37443815, 2023).
KRT27 also shares sentences with these, for which no sentence is quoted: periodontitis (2 papers); tumor (2); glioblastoma multiforme (1); glioma (1); Woolly hair (1).